CCND1 (cyclin D1)
Diseases named in the same sentence as CCND1 in open-access papers (continued):
Sharing a sentence is not in itself a finding about the gene and the disease.
breast cancer (continued). "The Cyclin D1 is overexpressed in up to 50% of breast cancer, and amplification of the CCND1 gene is associated with a poor patient outcome in several studies." (PMID 33317149, 2020). "More importantly, high expression of DILA1 was associated with overexpressed Cyclin D1 protein and poor prognosis in ER+ breast cancer patients who received tamoxifen." (PMID 33139730, 2020). "cyclin D1 overexpression occurs in a variety of human cancers and is linked to the development of tamoxifen resistance in ER+ breast cancer." (PMID 32929377, 2020). "Abnormal activation of the Wnt/beta-catenin signaling pathway breast tumorigenesis and subsequent upregulation of beta-catenin driven downstream targets-c-Myc and cyclin D1 is associated with the development of breast cancer." (PMID 32823812, 2020). "High levels of cyclin D1, for example, have been associated with increased mortality in breast cancer, and apoptosis resistance to tamoxifen and Doxo." (PMID 33204396, 2020). "To further clarify the underlying mechanism of miR-20b-5p in the regulation of breast cancer cells and stem cells, we chose CCND1 and E2F1 as potential targets based on bioinformatics analysis and preliminary screening by qRT-PCR." (PMID 33008330, 2020). "Of these genes and proteins, three are classically upregulated in breast cancer, and these are associated with poor prognosis in breast cancer: CCDN1/cyclin D1, PTPN11/SHP2, and RPS6KB1/S6K1." (PMID 33204396, 2020). "In order to assess the location of cyclin D1 in human breast cancer we compared membrane-associated cyclin D1 in patients with IBC and other breast cancers." (PMID 32948740, 2020). "High expression of DILA1 is associated with overexpressed Cyclin D1 protein and poor prognosis in breast cancer patients who received tamoxifen treatment." (PMID 33139730, 2020). "The human breast cancer cell line (MCF-7) was transduced with expression vectors encoding cyclin D1 targeted to the nucleus (Cherry-CD1NUC), to the cytoplasmic membrane (PECFP-CD1MEM) or expressed in both cytoplasmic and nuclear compartments (MSCV-CD1TOT)." (PMID 32948740, 2020). "The genetic deletion of EZH2 reportedly resulted in the down-regulation of cyclin D1 in breast cancer and caused the up-regulation of p21 in ovarian cancer, triggering cell-cycle arrest at the G1/S phase." (PMID 33330073, 2020). "The hormonal luminal-A is the most pre-dominant sub type of breast cancer (BC), and it is associated with a high level of cyclin D1 in Saudi patients." (PMID 33050377, 2020). "The frequency of CCND1 amplification and FANCA loss was higher in TPBCs than in ER-PR-HER2+ breast cancers (CCND1: 26% vs. 6%, P = 0.013; FANCA, 72% vs. 50%, P = 0.023)." (PMID 31410192, 2019). "CCND1 rs614367 is one of the strongest breast cancer risk loci identified by GWAS studies; however, its specific association with TNBC has not been identified." (PMID 31921621, 2019). "In line with this, the down-regulation of cyclin D1 protein expression was examined as one of the main factors that cause the growth inhibitory effect of sesamin against cyclin D1-depleted MCF-7 breast cancer cells." (PMID 31817084, 2019). "HACER highlights the breast cancer risk region targeting CCND1 and ranks all query regions by the availability of functional information." (PMID 30247654, 2019). "The CCND1 gene maps to the 11q13 breast cancer risk locus and the majority of breast tumours bearing amplification of the gene are oestrogen receptor (ER) positive, are of luminal B subtype, and overexpress cyclin D1 protein." (PMID 30819233, 2019). "CCND1, the cyclin D1 encoding gene, is frequently amplified in breast cancer, and depletion of cyclin D1 suppresses breast cancer progression." (PMID 31388935, 2019). "In the same cohort, the genotype of cyclin D1 (CCND1) was investigated for an association between genotype, breast cancer risk and interaction between risk and ω3 fatty acid consumption." (PMID 31505792, 2019).
breast cancer (continued). "In line with this proof of concept, we found that in patients with a low expression level of either BRCA1 or CCND1, the T cell activation score is negatively associated with the risk of mortality in breast cancer." (PMID 31023256, 2019). "We have previously found the same counterintuitive relationship between breast cancer risk alleles and CCND1 expression." (PMID 30988301, 2019). "A similar pattern was reported in human breast cancer cells, where OC exposure resulted in G1/M arrest that was associated with modulations of cyclin D1, p21 and p27 expression." (PMID 31653043, 2019). "Amplification or overexpression of cyclin D1 is strongly associated with short survival in breast cancer patients." (PMID 30018827, 2018). "The overexpression of cyclin D1 is associated with the development of resistance by the endocrine system in breast cancer cells." (PMID 29996919, 2018). "Similar to our results, Sergentanis and Economopoulos (2011) found that the ‘A’ allele of the CCND1 G870A polymorphism is associated with higher risk for breast cancer." (PMID 30361291, 2018). "β-Catenin is a marker of poor prognosis in human cancer and has been implicated in human breast cancer, via targeting cyclin D1 or vimentin." (PMID 30181805, 2018). "In both cases ATR-deficient cells enhanced the growth of breast cancer cells, which was confirmed by showing the expression of high levels of Ki-67 and cyclin D1." (PMID 30410668, 2018). "Cyclin D1 is a critical regulator essential for G1 phase progression and has a causative role in breast cancer formation." (PMID 28184196, 2017). "Knockdown of PHD1 in breast cancer cell lines reduces cell proliferation and this correlates with loss of cyclin D1." (PMID 28536364, 2017). "Expression of cyclin D1 above the median (61.7%) in ER breast cancer was associated with an increased risk for breast cancer death (OR 3.2 95% CI 1.5–6.8) also when adjusted for tumor size and grade (OR 3.1)." (PMID 28528450, 2017). "In primary breast cancer, it has been shown that the gene encoding cyclin D1 is amplified in 15% of the cases and overexpressed in 30–50%." (PMID 28797035, 2017). "Previously, some studies focused on the susceptibility of the Cyclin D1 (CCND1) G870A gene polymorphism to several type of cancer, including bladder cancer, breast cancer, colorectal cancer, leukemia and lung cancer." (PMID 28380465, 2017). "Cyclin D1 expression remained significantly associated to breast cancer mortality in ER-positive cases also when analyzed as a continuous variable in univariable (p = 0.01) and multivariable (p = 0.03) analyses (data not shown)." (PMID 28528450, 2017). "Of note, elevated levels of cyclin D1 protein have been associated with poor prognosis, whilst overexpression of cyclin D1 has been more commonly found in hormone receptor (HR) positive breast cancer cases." (PMID 28797035, 2017). "In summary, our results indicate that cyclin D1 overexpression is associated with types of breast cancer with good prognostic features (ER, PR, low grade), but appears to play different prognostic roles in different molecular subtypes." (PMID 29140993, 2017). "CCND1 is a frequently amplified gene in breast cancer and has been previously shown to be associated with improved disease-free and overall survival." (PMID 28697743, 2017). "CCND1, which encodes cyclin D1, is the target of miR-503 in breast cancer cells and endometrioid endometrial cancer." (PMID 28602785, 2017). "Consistently, we recently demonstrated that DMTF1α inhibits EBRR2-induced mammary tumorigenesis and DMTF1 loss promotes breast cancer development mediated by CCND1 overexpression." (PMID 28257090, 2017).
breast cancer (continued). "We confirmed our previous observation that high cyclin D1 expression is associated to high proliferation and a threefold higher risk of death from breast cancer in ER-positive breast cancer." (PMID 28528450, 2017). "Functional variants at the 11q13 risk locus for breast cancer downregulate cyclin D1 expression through long-range enhancers." (PMID 29299175, 2017). "TGFBR2 and CCND1 showed significant associations with overall breast cancer risk (p value <10−6 and 3.0 × 10−4, respectively)." (PMID 26621531, 2016). "Overexpression of cyclin D1 predominates in breast cancer, while loss of p16INK4a predominates in melanoma." (PMID 29263893, 2016). "The overexpression of cyclin D1 has been linked to the development and progression of breast cancer." (PMID 26910843, 2016). "Cisplatin-induced breast cancer cell death is associated with a decrease in the expression levels of CCND1." (PMID 26799586, 2016). "c-MYC and cyclin D1 are two major oncogenes, which confer proliferative and anti-apoptosis capacities to breast cancer cells, and are associated with altered sensitivity to endocrine therapy." (PMID 27465411, 2016). "It has been reported that the growth inhibition of lycopene on MCF-7 breast cancer cells was also associated with decreased G1-S cell cycle progression, decreased cyclin D1 expression, and stabilization of p27 in the cyclin E-CDK complex." (PMID 26664697, 2016). "PTEN deletions were inversely associated with features of luminal type breast cancers (ER/PR positivity; p < 0.0001 each, and CCND1 amplification; p = 0.0020)." (PMID 26672755, 2015). "In resectable breast cancer relatively brief exposure to the NSAID etodolac was associated with reduced cyclin D1 protein levels." (PMID 26275572, 2015). "This noting is supported by the fact that CCND1 amplification is strongly linked to hormone receptor (ER/PR) positive breast cancers, while HER2 and/or MYC (like PTEN deletions in our study) are more often found in ER-negative than in ER-positive cancers." (PMID 26672755, 2015). "In a breast cancer study, Lin and colleagues demonstrated that β-catenin modulated cyclin D1 expression; later, Yook and associates found that the Wnt cascade regulates Snail1 activity." (PMID 25605017, 2015). "An association between the expression of cyclin D1, β-catenin, and ER-β receptors in breast cancer cells was observed." (PMID 26404249, 2015). "Many of the genes in the RRHGE gene signature are already defined as well-known oncogenes, such as AR, BRCA1, CDK2, and CCND1, besides others, whose differential expression has been associated with the subtypes of breast cancer." (PMID 24563630, 2014). "Sicinski’s laboratory investigated the relationship of cyclin D1 genetic loss with the development of mammary tumors in mice whose tumors were driven by multiple different genetic stresses." (PMID 25223380, 2014). "The YAP1 gene is located at 11q22, a region often deleted upon amplification of the 11q13 region harbouring the known oncogene cyclin D1 gene (CCND1), which is amplified in 8-15% of all breast cancers and associated with a worse prognosis." (PMID 24559095, 2014). "The CCND1 gene is located on human chromosome 11q13 and has been associated with numerous types of cancer, and has been shown to be expressed in 5–23% of breast cancer patients." (PMID 25202398, 2014). "In this hospital-based case-control study, our team has genotyped a famous SNP CCND1 A870G studying its association with Taiwanese breast cancer risk in central Taiwan." (PMID 25520916, 2014). "Despite the fact our investigation revealed that Bmi1 expression is determined by ERα status in breast cancer, it must be noted that nearly half of the cases with loss of ERα still expressed Bmi1 or cyclin D1 which is another ERα target gene." (PMID 24559156, 2014).
breast cancer (continued). "Upregulation of cyclin D1 has been shown to shorten the G1 phase and is linked to development and progression of many types of cancer, such as breast cancer, gastric cancer and mantle cell lymphoma." (PMID 25438156, 2014). "Previous studies have demonstrated that CCND1 G870A polymorphism is significantly associated with the development of various cancers, such as breast cancer, prostate cancer, colorectal cancer, and other cancer types." (PMID 25204741, 2014). "The results of several studies suggest that cyclin D1 is overexpressed in breast cancer and that it is associated with ER positivity in breast cancer." (PMID 25009600, 2014). "Simple analysis of TCGA datasets indicates that luminal B cancers are over-represented for cyclin D1 amplification and loss of p16ink4a or RB relative to luminal A breast cancer." (PMID 25223380, 2014). "We found that TBLR1 expression was implicated in the upregulation of cyclin D1, phosphorylation of cell-cycle control protein Rb (pRb) and activation of β-catenin signaling in breast cancer." (PMID 25341494, 2014). "Several meta-analyses have revealed the associations between CCND1 G870A polymorphism and cancer risk, including lung cancer, oral cancer, esophageal cancer and breast cancer." (PMID 25409185, 2014). "This study’s genotyping work ascertained correlation between CCND1 A870G (rs9344) polymorphism and breast cancer risk in Taiwanese women." (PMID 25520916, 2014). "Gene amplification of CCND1 has been reported to be associated with an increased risk of breast cancer recurrence, while nuclear expression of cyclin D1 protein was associated with a decreased recurrence rate." (PMID 23336272, 2013). "Overexpression of cyclin D1 has earlier been associated with breast cancer subtypes that are more indolent, estrogen receptor positive, and have a better prognosis, and our findings pointed to a similar pattern." (PMID 23336272, 2013). "Patients within the ER+ subgroup who received endocrine therapy for their primary or recurrent breast cancers showed an association between high cyclin D1 and a shorter response duration." (PMID 23886499, 2013). "The CCND1 gene, which encodes for cyclin D1, is amplified in approximately 10-15% of breast cancers, most of which are ER+." (PMID 24367492, 2013). "The alteration of both cyclin D1 and cyclin E was associated with breast cancer progression, early relapse, poor prognosis and chemo-resistance to various cytotoxic agents." (PMID 24138843, 2013). "Further analysis is warranted and necessary to determine the efficacy of combination therapy in a cohort of patients with luminal breast cancers associated with CCND1 accumulation." (PMID 23390492, 2013). "We demonstrated that in the context of TGFβ signaling, cyclin D1 associates with p21 in metastatic breast cancer cells." (PMID 23786849, 2013). "Aberrant amplification and over-expression of cyclin D1 is a driving force in 13–20% of human breast cancers, and is associated with poor disease outcome." (PMID 24213463, 2012). "The proto-oncogene cyclin D1 is overexpressed in response to estrogen activation in human estrogen receptor (ERα) positive breast cancers and is associated with the mitogenic effects of ERα and onset of carcinogenesis." (PMID 22860097, 2012). "APN treatment of MDA-MB-231 breast cancer cells inhibits the phosphorylation of GSK3β, resulting in the degradation of β-catenin and subsequently causes the decrease of cyclin D1 expression." (PMID 23691481, 2012). "Cyclin D1 encodes a key regulator of the cell cycle transition from G1 to S phase and is overexpressed in more than 50% of breast cancers, functioning as a rate-limiting factor for human breast cancer cell proliferation in vivo and in vitro." (PMID 22260523, 2012). "In line with these experimental findings we have previously observed that cyclin D1 overexpression was associated with tamoxifen resistance in premenopausal and postmenopausal breast cancer." (PMID 22475046, 2012).
breast cancer (continued). "In about 15% of all primary breast cancers, overexpression is due to amplification of the corresponding gene CCND1, and this specific amplification has been linked to poor prognosis." (PMID 22475046, 2012). "Cyclin D1 is an important mitogen in breast cancers and is associated with poor prognosis in breast cancer patients." (PMID 22860097, 2012). "Further confusing matters, tumors high in cyclin D1 protein have been linked with resistance to endocrine therapy and shorter recurrence-free survival of breast cancer patients." (PMID 22924091, 2012). "P14ARF also induces the expression of the proto-oncogene cyclin D1, which is most often associated with a transition from G1-S phase and is highly expressed in breast cancers with poor clinical prognosis." (PMID 22860097, 2012). "In our study, we did not observe significant association between polymorphisms in NCOA3 and CCND1 with breast cancer risk." (PMID 21269472, 2011). "This assumption is supported by previous studies in breast cancer, which showed an association between low cyclin D1 levels and a more invasive tumor phenotype." (PMID 21888663, 2011). "ER has been shown to activate genes associated with proliferation (for example, Cyclin D1) and with anti-apoptosis (for example, Bcl2 and survivin) in breast cancer cells." (PMID 22123186, 2011). "Amplification of the chromosomal region on 11q13 is frequently observed in human cancers including HNSCC and breast cancer, and it is well known that CCND1, encoding cyclin D1, is a putative oncogene in the 11q13 amplicon." (PMID 21847129, 2011). "Cyclin D1 is one of the key regulators of the G1/S transition, and gene amplification or overexpression of cyclin D1 is associated with cell growth and tumorigenesis in breast cancer." (PMID 21980430, 2011). "In anti-estrogen-responsive breast cancers, tamoxifen causes a reduction in cyclin D1 expression, reducing CDK4/6 activity and promoting p27Kip1/p21Waf1/Cip1 inhibition of CDK2, resulting in decreased pRb phosphorylation and G1 cell cycle arrest." (PMID 20010939, 2010). "Overexpression of CCND1 induces mammary tumorigenesis, in addition, increased levels of CCND1 in ERα (estrogen receptor α)-positive breast cancer is associated with poor prognosis." (PMID 20353609, 2010). "In transgenic mouse models, inhibition of cyclin D1 proteolysis is the causative factor for mammary carcinomas and B-cell lymphomas." (PMID 20459741, 2010). "Aside from CCND1, coding variation in only a small number of these genes has been investigated in relation to breast cancer risk." (PMID 19183483, 2009). "Of interest, Wang and colleagues recently described a cyclin D1 splice variant - named cyclin D1b - that occurs in breast cancer tissue and cell lines, and whose expression can overcome cell cycle arrest induced by anti-estrogens via a CDK4 interaction." (PMID 19874578, 2009). "Both CDKIs are required for cyclin D assembly with CDK4 and its stability and nuclear localization, and p27 levels were significantly associated with cyclin D1 and E expression in some breast cancer cell lines." (PMID 20300579, 2009). "There are also reports showing that overexpression of cyclin D1 predicts tamoxifen treatment resistance in breast cancer patients and associates with poor prognostic features in estrogen receptor positive breast cancer." (PMID 19615042, 2009). "The cyclin D1 gene is amplified in 15% of breast cancers and up-regulation of cyclin D1 is associated with large fractions of breast, ovarian, and other cancers." (PMID 19194508, 2009). "Western blot analysis of MCF-7 human breast carcinoma cells in culture showed that 2 h pretreatment of auraptene (10 μM) resulted in nearly a total loss of IGF-1 induced cyclin D1 expression at 8 h." (PMID 19640308, 2009).